BRAF (B-Raf proto-oncogene, serine/threonine kinase)
Diseases named in the same sentence as BRAF in open-access papers (continued):
Sharing a sentence is not in itself a finding about the gene and the disease.
dysplastic nevi (14 papers, 2009 to 2025). "This study showed that there is a statistically significant difference in the frequency of BRAF mutations between patients with dysplastic nevi and those with melanoma in situ." (PMID 39200941, 2024). "According to the results, 3.3% of the patients with congenital nevi and 26.7% of the subjects with dysplastic nevi were positive for BRAF V600E mutation." (PMID 33391380, 2021). "The findings of the current study revealed the prevalence of BRAF V600E mutation as 14.3% in men and 37.5% in women with dysplastic nevi with a significant difference (P=0.226)." (PMID 33391380, 2021). "On the other hand, the remarkable prevalence of 26.7% was shown for BRAF V600E mutation in patients with dysplastic nevi." (PMID 33391380, 2021). "The high prevalence of BRAF V600E mutation in patients with dysplastic nevi was documented in several studies." (PMID 33391380, 2021). "According to the literature, the BRAF V600E mutation is frequent not only in acquired benign and dysplastic nevi but also in congenital nevi." (PMID 33391380, 2021). "According to the results of the current study, 3.3% of the patients with congenital nevi and 26.7% of dysplastic nevi cases were positive for BRAF V600E mutation." (PMID 33391380, 2021). "Moreover, in the dysplastic nevi group, the presence of BRAF gene mutation (V600E) showed a significant relationship with the severity of dysplasia as the mutation rate was 25% in mild cases, in comparison with 54.5% in moderate dysplasia cases (P=0.009)." (PMID 33391380, 2021). "The prevalence of BRAF gene (V600E) mutation was found as 1 case (3.3%) in congenital and 8 cases (26.7%) in dysplastic nevi indicating the higher prevalence of this mutation in patients with dysplastic nevi (P=0.026)." (PMID 33391380, 2021). "The prevalence of BRAF V600E mutation was one case (3.3%) in the congenital group and eight cases (26.7%) in the dysplastic group indicating the higher prevalence of this mutation in patients with dysplastic nevi (P=0.026)." (PMID 33391380, 2021). "Presence of BRAF mutations in benign and dysplastic nevi supports the hypothesis that activation of the NRAS-BRAF-ERK pathway is not sufficient to induce the malignant process and fully transform proliferating melanocytes, but requires additional, cooperating de-regulative events." (PMID 19799798, 2009). "There is not a statistically significant difference in the number of BRAF mutations between people who have dysplastic nevi and people who have melanoma in situ (if lentigo maligna (LM) is taken out of the equation)." (PMID 39200941, 2024). "It is noteworthy that in the dysplastic nevi group, the subgroups with and without BRAF V600E mutation had a significant difference in the severity of dysplasia as the rate of mutation was 25% in mild dysplasia and 54.5% in moderate dysplasia cases." (PMID 33391380, 2021). "Interestingly, the same relationship with B-Raf proto-oncogene (BRAF) status was observed in dysplastic nevi, with 92% of BRAFV600E samples being positive for phosphorylated DRP1S616." (PMID 29466320, 2018). "Our goal was to determine and compare the frequency of BRAF gene mutations in dysplastic nevi (ND) and melanomas in situ (MIS), as well as whether there is a correlation between the presence of BRAF gene mutations and various anamnestic, clinical, and histopathologic variables." (PMID 39200941, 2024).
intrahepatic cholangiocarcinoma (14 papers, 2014 to 2026). A carcinoma that arises from the intrahepatic bile duct epithelium in any site of the intrahepatic biliary tree. "BRAF mutations, particularly BRAF V600E, are rare but clinically significant molecular alterations in intrahepatic cholangiocarcinoma (IHCC), often linked to aggressive disease and poor prognosis." (PMID 40688855, 2025). "A previous study evaluating clinical outcomes in patients with BRAF-mutated intrahepatic cholangiocarcinoma reported that V600E was associated with larger, more invasive tumors and poorer overall survival when compared to non-V600E mutations." (PMID 38791902, 2024). "This cohort study examines BRAF variant subtypes, classifying them and analyzing response to therapy in patients with intrahepatic cholangiocarcinoma." (PMID 36867406, 2023). "Another group used an in-house-developed panel to identify a BRAF V600E mutation in a patient with intrahepatic cholangiocarcinoma (ICC)." (PMID 26404381, 2015). "Similar oncogenic drivers, including mutations in KRAS, BRAF, and HER2 (ERBB2), have been identified in intrahepatic cholangiocarcinoma (iCCA)." (PMID 41373672, 2025). "This is the case of a 47-year-old woman diagnosed with chemotherapy and radiation-refractory BRAF V600E mutant, poorly differentiated intrahepatic cholangiocarcinoma (ICC), with multiple metastatic lesions within the liver, lungs, pleura, and bone, stage IV." (PMID 25435907, 2014). "We did not see any case harboring BRAF V600E mutation, a rare occurrence restricted in intrahepatic cholangiocarcinoma." (PMID 34720757, 2021). "In BTCs, especially intrahepatic cholangiocarcinoma, comprehensive molecular profiling has expanded precision oncology through actionable alterations such as FGFR2 rearrangements, IDH1 mutations, HER2 amplification/overexpression, BRAF V600E, NTRK fusions, and MSI-high/dMMR status." (PMID 42196390, 2026). "Through a cohort study, the Zhou SL team evaluated broad differences among organoids with different BRAF variant subtypes in sensitivity to BRAF or MEK inhibitors, and suggested a precise treatment for patients with intrahepatic cholangiocarcinoma (ICC)." (PMID 38638528, 2024). "BRAF variants are associated with tumor progression; however, the prevalence of BRAF variant subtypes and their association with disease characteristics, prognosis, and targeted therapy response in patients with intrahepatic cholangiocarcinoma (ICC) are largely unknown." (PMID 36867406, 2023). "Importantly, the analysis of 300 liver cancer tissues—268 HCC, 24 intrahepatic cholangiocarcinoma (ICC), 8 of both types (HCC/ICC)—has identified new BRAF gene mutations for primary liver cancer." (PMID 35163468, 2022).
pancreatic adenocarcinoma (14 papers, 2014 to 2025). "Due to the rarity of these mutations, reported research on BRAF inhibitors in pancreatic adenocarcinoma is restricted primarily to case reports." (PMID 41367868, 2025). "Here, we report a case of an elderly patient with advanced pancreatic adenocarcinoma harboring a BRAF V600E mutation who received low-dose dabrafenib and trametinib and achieved satisfactory clinical outcomes." (PMID 41367868, 2025). "Here, we add a case to the growing literature describing an elderly patient with advanced pancreatic adenocarcinoma harboring a BRAF V600E mutation who received low-dose dabrafenib combined with trametinib and achieved clinical benefit." (PMID 41367868, 2025). "Among patients with KRAS wild-type pancreatic adenocarcinoma (representing 10% of all cases), 30% harbor BRAF mutations, accounting for 3% of all PAC." (PMID 41367868, 2025). "We aim to add a new case to the available literature with the hope of contributing to the growing discussion regarding the treatment of advanced pancreatic adenocarcinoma with BRAF mutations." (PMID 41367868, 2025). "In this report, we share a case of a 78-year-old patient with advanced pancreatic adenocarcinoma who refused chemotherapy due to advanced age and subsequently received low-dose dabrafenib combined with trametinib based on the presence of a BRAF V600E mutation." (PMID 41367868, 2025). "Dose-adjusted dabrafenib combined with trametinib might be a potentially effective treatment strategy for elderly patients with advanced pancreatic adenocarcinoma harboring BRAF V600E mutations, and needs to be further evaluated clinically." (PMID 41367868, 2025). "In pancreatic adenocarcinoma, about 3% of patients harbor the BRAF V600E mutations." (PMID 41367868, 2025). "In view of the successful experience of this case, we suggest that dose-adjusted dabrafenib plus trametinib might be a potentially effective treatment strategy for elderly patients with advanced pancreatic adenocarcinoma harboring BRAF V600E mutations." (PMID 41367868, 2025). "This case suggests that dose-adjusted dabrafenib combined with trametinib might be a potentially effective treatment strategy for elderly patients with advanced pancreatic adenocarcinoma harboring BRAF V600E mutations." (PMID 41367868, 2025). "We report a case of an elderly patient with BRAF V600E-mutant advanced pancreatic adenocarcinoma who received low-dose dabrafenib plus trametinib and achieved satisfactory clinical outcomes." (PMID 41367868, 2025). "We describe a 78-year-old female with BRAF V600E-mutant pancreatic adenocarcinoma." (PMID 41367868, 2025). "BRAF inhibitor therapy in pancreatic adenocarcinoma: a brief literature review." (PMID 41367868, 2025).
uveitis (14 papers, 2016 to 2025). An inflammatory process affecting a part of or the entire uvea. "Significant cases of uveitis or VKH-like syndrome linked to BRAF inhibitors or immunotherapy, vascular occlusions, or ischemic optic neuropathy caused by MEK inhibitors are of the greatest concern because they can cause permanent deterioration of vision, or even blindness." (PMID 39728071, 2024). "Uveitis was the most often reported irAEs associated with BRAF inhibitors in literature." (PMID 37347077, 2023). "Uveitis has been reported as a class effect of BRAF inhibitors, with the onset ranging from several weeks to months after treatment initiation." (PMID 39918770, 2025). "It is also known that certain antineoplastic drugs can mimic uveitis, such as vemurafenib (anti-BRAF), dabrafenib (anti-BRAF), nivolumab (anti-PD-1), ipilimumab (anti-CTLA-4), osimertinib (anti-EGFR), trametinib (anti-MEK), and rituximab (anti-CD20)." (PMID 40422265, 2025). "Among the ocular toxicities of BRAF inhibitors-another chemotherapeutic group-, uveitis and macular edema have been shown." (PMID 37046057, 2023). "The BRAF-inhibitor Vemurafenib, usually in combination with the MEK-inhibitor cobimetinib, was associated with both uveitis in 4% and with serous retinopathy in even 26%." (PMID 28818062, 2017). "BRAF/MEK inhibitor therapies are associated with a significant increase in the risk of uveitis, either anterior, intermediate uveitis with or without macular edema, papilledema." (PMID 38594487, 2024). "BRAF/MEK/ CHECK inhibitor therapies are associated with a significant increase in the risk of uveitis, either anterior, intermediate uveitis with or without macular edema, papilledema." (PMID 38594487, 2024). "Another retrospective case series showed a correlation between different cutaneous and extra-cutaneous adverse events including vitiligo, erythema nodosum, uveitis and keratitis sicca and the treatment outcome upon BRAF inhibitors either administered alone or in combination with MEK inhibitors." (PMID 34109122, 2021). "Vogt-Koyanagi-Harada (VKH)-like uveitis is uniquely reported with immune checkpoint inhibitors (ICI) and BRAF/MEK inhibitors." (PMID 40354015, 2025).
chronic lymphocytic leukemia (13 papers, 2013 to 2026). "Until now, it was thought that among B-cell neoplasms BRAF V600E mutation is almost entirely restricted to HCL, though individual BRAF V600E-mutant cases of chronic lymphocytic leukemia, prolymphocytic leukemia, classical Hodgkin lymphoma, and SMZL were also documented." (PMID 29556019, 2018). "In addition, BRAF mutations have also been detected in low frequency in other B-cell lymphomas, such as chronic lymphocytic leukemia and diffuse large B-cell lymphoma, but never in mantle cell lymphoma (MCL)." (PMID 38406519, 2024). "Sorafenib, developed as a BRAF inhibitor, reduces MCL1 translation leading to increased apoptosis in leukemia cells while Flavopiridol, a cyclin-dependent kinase inhibitor, suppresses MCL1 and has been used to treat patients with high-risk chronic lymphocytic leukemia (CLL)." (PMID 23762095, 2013).
dysplasia (13 papers, 2014 to 2025). A usually neoplastic transformation of the cell, associated with altered architectural tissue patterns. "Since SSA/P-derived dysplasia and adenocarcinoma, BRAF mutation is reported to show high incidence, we examined effect of CPE on BREF expression." (PMID 32481659, 2020). "Sessile serrated adenomas with BRAF mutation progress rapidly to cancer following the development of dysplasia (SSAD)." (PMID 29304767, 2018). "In conclusion, colorectal SSA/Ps with dysplasia and invasive carcinoma frequently harbored BRAF mutations and showed nuclear β-catenin expression." (PMID 30458818, 2018). "SSA/Ps with dysplasia/carcinoma frequently harbored BRAF mutations." (PMID 30458818, 2018). "Taken together, these findings suggest that serrated dysplasia NOS may have distinct molecular features compared with SSL-like dysplasia, and a subset of these lesions could represent precursor lesions for BRAF-mutated MSS CRCs, potentially explaining their higher malignant potential." (PMID 40565166, 2025). "In contrast, most cases of SSL-like dysplasia in colitis-affected segments were found in men, although their locational and biological characteristics were similar to those of SSLs in colitis-unaffected segments (predominantly in the proximal colon and with BRAF mutation)." (PMID 36827302, 2023). "Among 26 lesions located in colitis-affected segments, most displayed SSL-like dysplasia (58%), typically proximal and associated with BRAF mutations, whereas TSA-like dysplasia was more distal and linked to KRAS mutations." (PMID 41303078, 2025). "Recent studies have shown associations of SSA/Ps and those with dysplasia/carcinoma with DNA methylation or lost protein expression of DNA-repair genes (i.e., MLH1), a CpG island methylator phenotype, and BRAF mutations." (PMID 30458818, 2018). "BRAF mutations were observed in 75% (3/4) of cases of SSL-like dysplasia in colitis-affected segments and in all SSLs in colitis-unaffected segments, whereas KRAS mutations were observed in all cases of TSA-like dysplasia in colitis-affected segments and in all TSAs in colitis-unaffected segments." (PMID 36827302, 2023).
pituitary adenomas (13 papers, 2010 to 2023). "The transcript of BRAF is overexpressed in pituitary adenomas compared to normal pituitary, and the BRAFV600E mutation was found in 16.5% of corticotroph adenomas." (PMID 37958702, 2023). "Regarding pituitary adenomas, previous studies have detected low BRAF mutation rates." (PMID 29593792, 2018). "Taken together, these results indicate that BRAF V600E contribute to the pathogenesis of ACTH-secreting pituitary adenomas through increased phosphorylation of POMC transcription regulators including Nur77, c-jun, and c-fos." (PMID 30093687, 2018). "The oncogenic V600E BRAF mutation has been identified in 16.5% of corticotroph adenomas but not in other types of pituitary adenomas." (PMID 32012988, 2020). "In our samples, the most common oncotype was PTC (2 out of 3 cases) with a high frequency (2 out of 2 PTC samples) of the BRAF V600E mutation, whereas no mutation was detected in the pituitary adenoma biopsies of the same patients." (PMID 29593792, 2018). "In the total cohort, the most common oncotype in pituitary adenoma-related DTC was classical-variant PTC (9 out of 14 cases) with a high frequency (42.9%, 6/14) of BRAF (p.V600E) mutations, whereas none of these cases harbored NRAS mutations." (PMID 32333269, 2020). "However, neither BRAF V600E nor USP48 M415I/M415V was detected in other types of pituitary adenomas." (PMID 30093687, 2018).
viral infection (13 papers, 2011 to 2025). "However, recent data indicate both LCH and pulmonary LCH harbor the BRAF V600E and NRAS mutation and appear linked to external stimuli such as viral infection and cigarette smoking." (PMID 30134914, 2018). "Thus, both LCH and pulmonary LCH harbor the BRAF V600E mutation and NRAS mutation and appear related to external stimuli such as viral infection and cigarette smoking." (PMID 30134914, 2018). "By contrast, neither mutations in BRAF or NRAS nor an involvement of viral infection were found." (PMID 24535703, 2014). "Sorafenib has been identified as RAF1 and BRaf protein kinase inhibitor and has been reported to inhibit viral infectivity by downregulating ERK/MAPK signaling pathways during viral infection." (PMID 34067609, 2021). "BRAF inhibition, but not viral infection or UVB light, activated ERK1/2, whereas γH2AX expression, inducible by UVB light, remained unaltered by BRAFis." (PMID 39335105, 2024). "All of these data thus indicate that the inhibitory effect of vemurafenib is not due to the inhibition of BRAF signaling, but instead, the virus infection is inhibited by other mechanisms." (PMID 37436162, 2023). "Interestingly, the antiviral effect of BRAFV600E inhibitor vemurafenib was not related to the inhibition of the BRAF kinase since the virus infection was efficiently inhibited in a cell line (A549) that does not contain the V600E mutation of BRAF." (PMID 37436162, 2023). "In contrast, significantly fewer tumors were observed in the absence of either BRAF inhibition, UVB irradiation or virus infection, as demonstrated by lesional outgrowth in 20%, 5% and 0% of the mice, respectively." (PMID 39335105, 2024).
ependymoma (12 papers, 2019 to 2025). A WHO grade II, slow growing tumor of children and young adults, usually located intraventricularly. "We show that most cases will likely be resolved by careful histopathologic analysis and the use of immunohistochemical stains, including surrogate stains for histone 3, IDH1 and BRAF mutations, and subtype-specific stains for ependymoma and medulloblastoma." (PMID 38764578, 2024). "RELA ependymomas can be further differentiated from other AB pseudorosette-predominant lesions by BRAF mutational analysis, FISH for MN1 rearrangement, or genomic DNA methylation analysis." (PMID 30876455, 2019). "Patient 19 with an ependymoma CNS WHO grade 3 and a BRAF K601E mutation in the panel sequencing analysis was treated with trametinib for two months until tumor progression." (PMID 35864412, 2022).
head and neck squamous cell carcinoma (12 papers, 2012 to 2025). A squamous cell carcinoma that arises from any of the following anatomic sites: lip and oral cavity, nasal cavity, paranasal sinuses, pharynx, larynx, and salivary glands. "The results indicated that the methylation of BRAF was down-regulated in LUSC, head and neck squamous cell carcinoma (HNSC), and UCEC." (PMID 35910024, 2022). "TRIM22 and BRAF are novel fusion partners; however, TRIM22 has been reported with other fusion partners in head/neck squamous cell carcinoma." (PMID 34863095, 2021). "Besides, WEE1 inhibition effectively reversed resistance to BRAF inhibitors and AURKA inhibitor (MLN8237) in HPV- HNSCC (head and neck squamous cell carcinoma." (PMID 38231277, 2024).
osteosarcoma (12 papers, 2011 to 2025). A usually aggressive malignant bone-forming mesenchymal neoplasm, predominantly affecting adolescents and young adults. "Patients in cohort 4 (BRAF-altered LGG) were treated by the combination of BRAF/MEK inhibitors (dabrafenib and trametinib), and patients in cohort 5 (osteosarcoma) were treated with the MTKI regorafenib." (PMID 37399010, 2023).